ERMP1 (endoplasmic reticulum metallopeptidase 1)
Description:
Within the ovary, required for the organization of somatic cells and oocytes into discrete follicular structures.
Synonyms: FXNA; KIAA1815; FLJ23309; bA207C16.3
Tractability: Antibody: UniProt predicts a signal peptide or a membrane-spanning region. PROTAC: ubiquitination databases record sites on it; its protein half-life has been measured.
Target class: Enzyme; Hydrolase
Gene: Protein-coding gene on chromosome 9 (5,749,832 to 5,879,537, reverse strand). Ensembl gene ENSG00000099219.
Subcellular location: Endoplasmic reticulum membrane
Gene Ontology:
Molecular function: protein binding; metalloexopeptidase activity
Biological process: cellular response to oxidative stress; endoplasmic reticulum unfolded protein response; proteolysis
Cellular component: membrane; endoplasmic reticulum membrane
Genetic constraint (gnomAD): Loss-of-function variants: 77 observed, 75.13 expected, observed/expected ratio (o/e) 1.02, 90% interval 0.85 to 1.24. The synonymous counts are far from expectation, so gnomAD's model fits this gene poorly and the ratio says little. Missense variants: 1,240 observed, 1,029.8 expected, observed/expected ratio (o/e) 1.2, 90% interval 1.15 to 1.26. Synonymous variants: 496 observed, 378.82 expected, observed/expected ratio (o/e) 1.31, 90% interval 1.22 to 1.41.
Homologues: Orthologues: chimpanzee ERMP1 (99% identical), macaque ERMP1 (97% identical), rabbit ERMP1 (92% identical), dog ERMP1 (91% identical), pig ERMP1 (90% identical), guinea pig ERMP1 (87% identical), rat Ermp1 (86% identical), mouse Ermp1 (85% identical), tropical clawed frog ermp1 (62% identical), Caenorhabditis elegans B0495.7 (30% identical), Drosophila melanogaster CG30047 (29% identical), Drosophila melanogaster CG30043 (29% identical), and 9 more.
Diseases named in the same sentence as ERMP1 in open-access papers:
ERMP1 is named in the same sentence as 16 diseases in open-access papers, as found by Europe PMC text mining. Sharing a sentence is not in itself a finding about the gene and the disease. The quoted sentences say what the papers report.
liver cancer (3 papers, 2016 to 2021). An epithelial or non-epithelial malignant neoplasm that arises from the liver. "MiRmiR-328-3p inhibits metastasis in colorectal cancer via inactivation of the PI3K/Akt signaling pathway and reduces invasion as well as EMT in liver cancer via by targeting endoplasmatic reticulum metallo protease 1 (ERMP1) to inhibit AKT phosphorylation." (PMID 33807023, 2021). "For examples, in osteosarcoma, colorectal cancer, liver cancer and breast cancer, miR-328-3p overexpression inhibited their migration, invasion, and EMT by directly inhibiting MMP-16, Girdin, Endoplasmic Reticulum Metallo Protease 1 (ERMP1) and CD44, respectively 17, 26-29." (PMID 34659543, 2021).
breast carcinoma (2 papers, 2016 to 2021). "ERMP1 gene maps at chromosome 9p24, a locus recently described as a novel amplicon in human esophageal and breast cancers." (PMID 27566589, 2016). "Studies in human esophageal and breast cancers showed that ERMP1 gene is located in the 9p24 genomic amplicon." (PMID 27566589, 2016). "In breast cancer, ERMP1 was detected in 94.2% of the cases, 42.3% showed a strong or moderate staining." (PMID 27566589, 2016). "In breast cancer the 9p24 genomic amplicon contains six genes, among which ERMP1 and IL33 are overexpressed independently of the copy number increase, while GASC1, UHRF2, KIAA1432 and C9orf123 are overexpressed only in the context of gene amplification." (PMID 27566589, 2016). "The high MW band, similar in size to that detected in ERMP1-transfected HeLa cells, was clearly visible in 2/4 breast cancer samples, in 4/7 lung cancer samples and in 4/4 ovary cancer samples, but not or only marginally visible in the corresponding normal samples." (PMID 27566589, 2016). "In breast cancer, ERMP1 is expressed at similar frequency regardless of the expression of HER2, progesterone and estrogen receptors." (PMID 27566589, 2016). "Interestingly, ERMP1 showed a high/moderate staining in 57% of the triple negative (HER2-, ER-, PR- negative) breast cancer samples." (PMID 27566589, 2016).
endometrial cancer (2 papers, 2021 to 2024). Primary or metastatic malignant neoplasm involving the endometrium (mucous membrane that lines the endometrial cavity). "miR-148b suppressed cell proliferation and regulated the oxidative stress response in human endometrial cancer RL95-2 cells by inhibiting endoplasmic reticulum metalloprotease 1 (ERMP1) expression." (PMID 39308520, 2024).
asthma (1 paper, 2021). "Another interesting gene, ERMP1, has an eQTL colocalizing with an asthma GWAS association in the UK Biobank." (PMID 33883027, 2021).
colon cancers (1 paper, 2016). "In this study, we identified ERMP1 as a novel broadly tumor-associated-antigen, with high frequency in breast, ovary, lung and colon cancers independently from cancer stages and grades." (PMID 27566589, 2016). "Interestingly ERMP1 expression seems to be independent from important predictive biomarkers in breast as well as in colon cancer." (PMID 27566589, 2016). "In colon cancer, ERMP1 is expressed irrespective of KRAS and /or BRAF mutational status." (PMID 27566589, 2016).
ischemic stroke (1 paper, 2021). A stroke disorder caused by obstruction of blood flow to the brain, due to thrombotic (local blood clot formation) or embolic (due to a blood clot or other material traveling from another site) event. "It has been shown to attenuate ischemic stroke by directly targeting endoplasmic reticulum metallopeptidase 1 (ERMP1)-mediated endoplasmic reticulum stress." (PMID 34730612, 2021).
ovarian carcinoma (1 paper, 2016). A malignant neoplasm originating from the surface ovarian epithelium. "In ovarian cancer, ERMP1 was detected in 96.7% of the samples, with a strong to moderate staining in 35.3% of them and without association with pT stages." (PMID 27566589, 2016). "IHC data showed that ERMP1 is highly expressed in breast, colon, lung and ovary cancers." (PMID 27566589, 2016). "In this study, we demonstrate that Endoplasmic Reticulum Metallo Protease 1 (ERMP1) is broadly expressed in a high percentage of breast, colo-rectal, lung, and ovary cancers, regardless of their stage and grade." (PMID 27566589, 2016).
prostate carcinoma (1 paper, 2016). A carcinoma that arises from epithelial cells of the prostate gland. "Although not deeply investigated, our q-RT-PCR data indicate that ERMP1 is also upregulated in prostate cancer." (PMID 27566589, 2016).
cancer (5 papers, 2016 to 2026). A tumor composed of atypical neoplastic, often pleomorphic cells that invade other tissues. "The present study brings a substantial contribution to our current knowledge on ERMP1 and provides robust experimental evidence of its association with cancers with high morbidity and mortality rate." (PMID 27566589, 2016). "Moreover, we show that loss of ERMP1 expression significantly hampers proliferation, migration and invasiveness of cancer cells." (PMID 27566589, 2016). "The role of the ERMP1 protein in cancer proliferation and progression through the PI3K/AKT/mTOR/β-catenin signaling pathways has been identified as a promising therapeutic strategy for treating various types of cancer." (PMID 38785548, 2024). "In vitro studies have suggested that human ERMP1 increases the proliferation and invasion of cancer cells through the PIK3/AKT/mTOR/β-catenin pathway." (PMID 38785548, 2024). "ERMP1 is widely expressed in cancers, and is an important participant in the unfolded protein response." (PMID 37353812, 2023). "Endoplasmic reticulum metalloprotease 1(ERMP1) is located on chromosome 9p24 and is found to be an amplicon in cancers." (PMID 34585646, 2021). "In agreement with its predicted localization we found ERMP1 in the intracellular compartment of cancer cells by IHC and confocal microscopy." (PMID 27566589, 2016). "First, loss of ERMP1 expression caused by transient ERMP1 silencing significantly affects proliferation and invasiveness of ERMP1-positive cancer cells, suggesting a role of the protein in growth and propagation of cancer cells." (PMID 27566589, 2016). "A mouse monoclonal antibody (ERMP1 mAb) raised against rERMP1 by the conventional hybridoma technology and specific for rERMP1 (full details about the fine specificity are given below) was used to confirm ERMP1 expression in cancer tissues." (PMID 27566589, 2016). "Second, ERMP1 expression is affected by menadione- and thapsigargin-induced stresses, and by hypoxia stimuli mimicking conditions typically encountered by cancer cells in their natural environment, which are acknowledged stimuli of UPR." (PMID 27566589, 2016). "The ERMP1 mAb showed positive staining in breast (94%), colon (94%), lung (74%), and ovary (96%) cancer samples." (PMID 27566589, 2016). "The evidence that ERMP1 is a broadly and highly expressed in several cancer types suggests that it plays an important role in cell processes and pathways crucial for cancer development." (PMID 27566589, 2016). "In NSCLC cancer, ERMP1 was detected in 95.4% of the cases, 41.4% of which showed a strong or moderate staining." (PMID 27566589, 2016). "ERMP1 mAb specifically stained breast (4/5 positive), colon (3/5 positive), ovary (4/5 positive) and lung (3/5 positive) cancers, with a concomitant negligible staining in the corresponding normal samples." (PMID 27566589, 2016). "A prevalence analysis in these four tumor types showed that ERMP1 is expressed at similar level in early and late stages as well as in highly and poorly differentiated cancers." (PMID 27566589, 2016). "We then assessed ERMP1 localization by immunostaining and confocal microscopy analysis of selected cancer cell lines previously found to be ERMP1 positive by Western blot." (PMID 27566589, 2016). "In humans, these pathways are modified in some types of cancer due to ERMP1 overexpression, but the mechanism is unknown." (PMID 38785548, 2024). "Our data provide the rationale for the design of novel ERMP1-targeting drugs that could act by inhibiting the UPR initial adaptive response of cancer cells and impair cell survival." (PMID 27566589, 2016). "The effect of thapsigargin, menadione and hypoxia on ERMP1 expression in cancer cells led to the hypothesis that ERMP1 is involved in the UPR and in the response to oxidative stress." (PMID 27566589, 2016). "Overall, our study highlights ERMP1 as a novel target for anti-cancer therapies." (PMID 27566589, 2016).
cancer (continued). "The identification of the regulatory or environmental conditions that promote ERMP1 expression could contribute to elucidate its role in cancer cells." (PMID 27566589, 2016). "In accordance, ERMP1 transcript was found upregulated in these cancer types." (PMID 27566589, 2016). "In this context ERMP1, being highly expressed in cancer cells might be used to overcome the current limit of UPR targeting drugs." (PMID 27566589, 2016). "Collectively, higher expression levels f ERMP1 may suggest a poor prognosis in cancers." (PMID 34585646, 2021). "Moreover, since high expression of GRP78/BiP protect cancer cells from the cytotoxic effects of several chemotherapeutic agents, targeting ERMP1 could also weaken GRP78/BiP-dependent chemoresistance mechanisms of cancer cells." (PMID 27566589, 2016). "Moreover, they provide the rationale for the design of ERMP1-targeting drugs that could act by inhibiting the UPR initial adaptive response of cancer cells and impair cell survival." (PMID 27566589, 2016).
tumor (3 papers, 2016 to 2026). "We additionally investigated ERMP1 mRNA level in clinical samples from breast, lung, colon, ovary and prostate samples by q-RT-PCR (2 normal samples and 2-6 tumor samples for each organ)." (PMID 27566589, 2016). "In a first step a TMA carrying five duplicate tumor and the corresponding normal samples for each tumor type (breast, colon, lung, and ovary) were analyzed for their ERMP1 expression." (PMID 27566589, 2016). "In KIRC, ERMP1 may exert tumor-suppressive effects by inhibiting the PI3K/AKT signaling pathway and regulating immune responses, thus representing a potential prognostic biomarker and therapeutic target." (PMID 41960369, 2026). "We then investigated the role of ERMP1 in processes important for tumor development, such as proliferation, apoptosis and invasiveness, by gene silencing of SK-BR-3 and MCF7 cell lines with ERMP1-siRNAs or scramble siRNAs (1 nM)." (PMID 27566589, 2016). "Other genes, such as ASNS, EIF2AK4, ERMP1, and HYOU1, showed an increasing trend in tumor tissue, but this was not statistically significant." (PMID 35884393, 2022).
ERMP1 also shares sentences with these, for which no sentence is quoted: colorectal cancer (2 papers); COVID-19 (1); diabetes (1); lung carcinoma (1); non-small cell lung carcinoma (1); osteosarcoma (1).